BLID (BH3-like motif containing, cell death inducer)
Description:
Functions as a proapoptotic molecule through the caspase-dependent mitochondrial pathway of cell death.
Synonyms: BRCC2
Tractability: No criterion of Open Targets' tractability assessment is met for any kind of drug.
Gene: Protein-coding gene on chromosome 11 (122,115,340 to 122,116,215, reverse strand). Ensembl gene ENSG00000259571.
Subcellular location: Cytoplasm; Mitochondrion
Subcellular location (Human Protein Atlas): Cytosol
Gene Ontology:
Biological process: positive regulation of apoptotic process
Cellular component: cytosol; mitochondrion; cytoplasm
Genetic constraint (gnomAD): Loss-of-function variants: 1 observed, 1.08 expected, observed/expected ratio (o/e) 0.92, 90% interval 0.25 to 1.88. That is too few expected variants to judge how well the gene tolerates losing a copy. Missense variants: 133 observed, 131.75 expected, observed/expected ratio (o/e) 1.01, 90% interval 0.88 to 1.17. Synonymous variants: 47 observed, 50.13 expected, observed/expected ratio (o/e) 0.94, 90% interval 0.74 to 1.2.
Diseases named in the same sentence as BLID in open-access papers:
BLID is named in the same sentence as 7 diseases in open-access papers, as found by Europe PMC text mining. Sharing a sentence is not in itself a finding about the gene and the disease. The quoted sentences say what the papers report.
myopia (3 papers, 2009 to 2011). "BLID encodes an inducer of apoptotic cell death, and apoptosis is known to play an important functional role in pathological myopia." (PMID 19779542, 2009). "Although the susceptibility locus contains BLID and LOC399959, it seems premature to discuss the involvement of LOC399959 in myopia since it is a hypothetical non-coding gene." (PMID 19779542, 2009). "Therefore, although our findings did not confirm that the BLID and LOC399959 genes play a genetic role in Chinese patients with high myopia, we cannot rule out the possibility that other susceptibility genes in related molecular pathways may be involved." (PMID 21031016, 2010).
gastric cancer (1 paper, 2023). A primary or metastatic malignant neoplasm involving the stomach. "This study revealed the gastric cancer-associated lncRNA RNU12 is a tumor-suppressor lncRNA that inhibits cancer progression via miR-575/BLID axis, which plays crucial role in gastric cancer progression and suggest that RNU12 is potential GC marker and target for GC therapy." (PMID 37160927, 2023).
lung carcinoma (1 paper, 2019). "MiR-575 induced proliferation of lung cancer cell by down-regulation of BLID, which is a cell death inducer, supporting multiple functions of miR-575 in different cellular contexts." (PMID 30333257, 2019).
cancer (3 papers, 2023 to 2025). A tumor composed of atypical neoplastic, often pleomorphic cells that invade other tissues. "This lack of experimental evidence does suggest that BLID is most likely to be a non-coding cancer antigen." (PMID 39713347, 2024).
tumor (2 papers, 2020 to 2023). "BLID is a tumor-suppressor gene involved in DNA repair and gene integrity." (PMID 32368293, 2020). "Here, we explored the function of RNU12 in controlling the tumor growth and progression and found that RNU12, as a sponge of miR-575, reduced miR-575 expression, regulated BLID expression and reduced GC cell proliferation and metastasis." (PMID 37160927, 2023).
BLID also shares sentences with these, for which no sentence is quoted: cervical cancer (1 paper); Oral ulcer (1).